MMP9 (matrix metallopeptidase 9)
Diseases named in the same sentence as MMP9 in open-access papers (continued):
Sharing a sentence is not in itself a finding about the gene and the disease.
tumor (continued). "MMP-9 is a matrix metalloproteinase extensively studied due to its crucial role in tumor metastasis and cancer cell invasion." (PMID 38461536, 2024). "For instance, the IL-6, platelet-derived growth factor (PDGF), and matrix metalloproteinases (MT-MMPs) such as MMP-2, MMP-9, MMP-14 and alpha-1 type I collagen (encoded by COLA1) secreted by tumour cells are known to influence MSC activity." (PMID 39120301, 2024). "EGCG also inhibited the expression of MMP-9 at the mRNA and protein levels and downregulated the NF-κB pathway in the tumor lysate." (PMID 39335164, 2024). "CD44 is involved in cell-cell interactions and migration, and also activates MMP-9 which promotes tumor angiogenesis through TGF-β activation." (PMID 39758992, 2024). "MMP9 plays a critical role in extracellular matrix degradation, promoting tumor tissue invasion and metastasis." (PMID 38360888, 2024). "Among them, MMP-2 and MMP-9 blocked the expression of tight junction proteins claudin-5 and ZO-1, thus helping tumor cells to cross the BBB." (PMID 38243240, 2024). "Their results showed a positive correlation between the gelatinases and metastasis of this tumor similar to previous reports with MMP-9 being more specific and better indicating patient prognosis." (PMID 38611032, 2024). "Local basement membrane deterioration, a prerequisite for endothelial and tumor cell infiltration, is a function in which MMPs, including MMP9, are actively involved." (PMID 39664453, 2024). "In conclusion, MMP-9 plays a critical role in various biological processes, including inflammation, the injury response, tissue regeneration, tumor progression and immune regulation." (PMID 39712025, 2024). "This suggests MMP9’s role in tumor progression and matrix remodeling, highlighting its potential as a prognostic marker and therapeutic target." (PMID 39234567, 2024). "MMP9’s role in breaking down the extracellular matrix and promoting tumor growth and spread in CRC has been well documented." (PMID 39664453, 2024). "MMP2 and MMP9 play important roles in tumor invasion and metastasis by degrading collagen fibers cleaved by collagenase." (PMID 38429828, 2024). "The formation of pre-metastatic niches, the resurgence of dormant metastases, and the possibility for direct tumor growth via related proteases like NE and MMP9 via the proteolytic restructuring of laminin are all reliant on them." (PMID 39555072, 2024). "The main MMP family member that breaks down collagen and fibronectin to promote tumor migration is MMP-9." (PMID 39338293, 2024). "In this context, our previous research showed the role of methDNA in the modulation of the NGAL/SLC22A17/MMP-9 network in several tumor types." (PMID 39358721, 2024). "Results: we presented a single-cell atlas of advanced HCC, highlighting the expression patterns of MICA and MMP9 in tumor cells and macrophages, respectively." (PMID 38254761, 2024). "Its involvement in tumor proliferation and invasion revolves around the decrease in the functional activity of matrix metallopeptidase 9 (mmp9)." (PMID 38601769, 2024). "VEGFR2 activation enhances endothelial MMP9 expression in the tumor microenvironment, which degrades the ECM and facilitates metastatic dissemination." (PMID 38441970, 2024). "TAN promote tumor invasion and angiogenesis, as well as migration, through the production of matrix metalloproteinase-9 (MMP-9), vascular endothelial growth factor (VEGF), and hepatocyte growth factor (HGF) at both primary and metastatic sites." (PMID 39100676, 2024). "Differential analysis indicated that SLC16A3+ macrophages exhibit high expression of macrophage markers promoting migration, invasion and tumour angiogenesis, such as SPP1 and MMP9, as well as genes associated with glycolysis, including PKM." (PMID 39656344, 2024). "GHRL, KLF4, and DUSP5 expression levels were relatively lower in tumor tissues, whereas DSP, PERP, and MMP9 were highly expressed in tumor tissues." (PMID 38273348, 2024).
tumor (continued). "This PAR2-centric pathway offers a new perspective on the multifaceted regulation of MMP9, proposing that the local coagulation environment within the tumor contributes to the upregulation of MMP9, thereby enhancing the invasive capabilities of CRC cells." (PMID 39664453, 2024). "Gelatinases, specifically MMP-2 and MMP-9, play critical roles in the processes of tumor growth, invasion, and metastasis." (PMID 39858430, 2024). "We also performed in vitro treatment with M2c-macrophages and MMP9 inhibitors on EBV-positive tumour cells and subsequent VM formation assays." (PMID 39267775, 2024). "MMP-9 enhances the bioavailability of VEGF in the tumour microenvironment by hydrolysing the molecular binding domain of VEGF, thereby activating dormant tumour cells and triggering tumour metastasis." (PMID 38912060, 2024). "Traumatic surgery (such as biopsy) induces MDSC amplification produce angiogenic factors and matrix-degrading enzymes, such as VEGF and MMP-9, to promote tumor angiogenesis, allowing it to form a microenvironment that promotes tumor metastasis after biopsy." (PMID 38578317, 2024). "MMP2 and MMP9 play an important role in tumor invasion and metastasis by degrading fibrillar collagen after cleavage by collagenase." (PMID 38399294, 2024). "Conversely, neutrophils that aid tumor development secrete MMP-9, facilitating the growth of new blood vessels and the dissemination of tumor cells." (PMID 38835055, 2024). "For instance, MMP-2 and MMP-9 have been shown to promote tumor invasion and metastasis in breast cancer by degrading the ECM components and facilitating tumor cell migration." (PMID 39493455, 2024). "In breast cancer, the increasing of NF-κB activity leads to the higher expression of testes-specific protease 50 (TSP50) via regulating the secretion of MMP-9,which eventually promotes cell invasion and tumor metastasis." (PMID 39493763, 2024). "The proteolysis of collagen IV by the MMP-9 releases tumstatin that inhibits the endothelial cells and, therefore, tumor angiogenesis." (PMID 39063046, 2024). "The serpin E2/uPA covalent complex is decomposed after binding to low-density lipoprotein receptor-related protein 1 (LRP-1), stimulating ERK activation, promoting MMP9 expression, and aggravating tumor metastasis." (PMID 38469181, 2024). "Intriguingly, MMP9 expression was specifically upregulated in both tumor cells and CAFs only in the 3D co-cultures." (PMID 39700125, 2024). "Other than this, the expression of MMP2 and MMP9 in 4T1 tumor tissues was inhibited by garlic peel extracts and was positively correlated with the expression of COX‐2." (PMID 39554336, 2024). "Here, we observed that CAFs grown in 3D cultures upregulated a variety of MMPs such as MMP-1, MMP2, MMP3, and MMP9, which are major players in tumor angiogenesis, tissue remodeling, repair, and maintenance." (PMID 39700125, 2024). "The MMPs mainly involved in tumor invasion and present in invadopodia are certainly MMP-9 and MMP-2." (PMID 38540096, 2024). "When the pDM reached the tumor sites in 4T1 tumor-bearing mice, the PEG coating of the micelles was hydrolyzed under the action of MMP9, causing an increase in the concentration of DTX in tumor cells." (PMID 39337266, 2024). "Particularly in poorly differentiated carcinomas, MMP9’s expression pattern implicates it in the remodeling of the extracellular matrix and angiogenesis, which are crucial processes for tumor aggressiveness." (PMID 39664453, 2024). "Immunohistochemistry was employed to assess the expression levels of COX‐2, CD31, VEGFA, MMP2, and MMP9 in tumor tissues in order to investigate the antioxidant properties of garlic peel extract, specifically its ability to suppress COX‐2 expression." (PMID 39554336, 2024).
tumor (continued). "Neutrophils, in addition to the production of angiogenic cytokines like: vascular endothelial growth factor and interlukin-8 (IL-8), they also produce matrix metalloprotein-9 (MMP-9) (gelatinase B) that induces an angiogenic state in the tumour cells." (PMID 38616289, 2024). "In CRC, MMPs, particularly MMP-2 and MMP-9, are implicated in EMT, playing a role in the degradation of type IV collagen in the basement membrane and increasing tumor invasiveness." (PMID 38672844, 2024). "In tumors, MMP2 and MMP9 are involved in connective tissue degradation, tumor-induced angiogenesis, and cell migration." (PMID 38541002, 2024). "Analysis of CRC tumour tissues showed that the expression of MMP-9 is significantly higher compared to the adjacent healthy tissue." (PMID 39450334, 2024). "This was supported by decreased expression of matrix metalloproteinases MMP2 and MMP9, which play a role in tumor cell invasiveness and metastasis." (PMID 39796103, 2024). "Studies have shown that MMP-9 is superior to MMP-2 for tumor recurrence and survival prediction in HCC patients." (PMID 38461536, 2024). "MMP9 is the main enzyme able to remodel the extracellular matrix by favoring the tumor invasive processes." (PMID 38339136, 2024). "A key mechanism through which the NF-κB pathway encourages tumor invasion and metastasis is by elevating MMP9 expression." (PMID 38653973, 2024). "MMP9 degrades the ECM near tumors, which are intimately associated with tumor invasion and metastasis, performs the final degradation of collagen fibers, and removes malignant cells from the complicated network around them." (PMID 39257397, 2024). "By degrading type IV collagen and denatured collagen molecules, MMP9 facilitates tumor cell invasion into surrounding tissues and metastasis." (PMID 39664453, 2024). "Andecaliximab (ADX), a monoclonal antibody, suppresses the extracellular enzyme MMP9, which has an essential function in matrix remodeling, tumor development, and metastasis." (PMID 38956384, 2024). "The activation of the MAPK/ERK pathway is known to contribute to the immune evasion potential of tumor cells, which was further diminished by hesperidin and reduced secretion levels of MMP-9 and MMP-2 in high PD-L1 expressing tumor cells." (PMID 39690423, 2024). "On the contrary, individuals with greater social support exhibited reduced levels of vascular endothelial growth factor (VEGF) and MMP-9 in tumor cells." (PMID 38254696, 2024). "Conversely, in cancer, components such as NE and MMP-9 assume pivotal roles in fostering tumor cell proliferation, metastasis, angiogenesis, and the reactivation of dormant tumor cells." (PMID 38672433, 2024). "In invasive lung adenocarcinoma, the proportion of CAFs and matrix metalloproteinase 9 (MMP9) expression is increased, suggesting a significant role in tumor invasion." (PMID 39834587, 2024). "MMP-9 is found in keratinocytes, fibroblasts, hematopoietic, immune cells (neutrophils, macrophages, lymphocytes), and tumor cells." (PMID 39063046, 2024). "MMPs and gelatinase B/MMP-9 actively degrade the extracellular matrix, promoting tumor invasiveness and metastasis." (PMID 38533507, 2024). "The short peptide sequence PLGLAG is an MMP2/MMP9-sensitive linking fragment that can be cleaved in tumor tissue." (PMID 38429828, 2024). "Our study has examined both cell migration and invasion, anchorage-independent tumor growth, and active MMP-9 production (via gelatin zymography) using BCG immunotherapy compared to another mycobacterium-based antitumor agent." (PMID 39684712, 2024). "In solid tumors, MMP-9 can release VEGF and FGF-2 sequestered in the extracellular matrix, which in turn activate tumor-associated ECs." (PMID 39796700, 2024). "Numerous studies have clarified the molecular mechanisms by which SNAI1 regulates EMT, including the upregulation of matrix metalloproteinase genes such as MMP9, which degrade the basement membrane and stimulate tumor cell invasion." (PMID 39722890, 2024).
tumor (continued). "M2 subtypes have characteristics that are mostly anti-inflammatory and pro-angiogenic, secreting growth factors (VEGF, PDGF) and matrix metalloproteinases (MMP2, MMP9) promoting tumor growth, metastasis, and invasion." (PMID 38935134, 2024). "Neutrophil cluster (10.2%; range 0.2-29.3%; n=8) infiltrating tumor tissues were identified based on the expression of CD66b and high levels MMP-9 stored into their tertiary granules." (PMID 39575252, 2024). "The study of the immunodetection of metalloproteases in PC-3 tumours revealed that the combined treatment caused a decrease in MMP-2 and MMP-9; in the latter case, this was similar, although somewhat weaker, to that obtained after treatment with MIA-690." (PMID 39456984, 2024). "MMP9 plays an important role in extracellular matrix (ECM) remodeling and is associated with tumor invasion, metastasis, and tumor micro-environment modulation." (PMID 38247865, 2024). "Specifically, it has been demonstrated to downregulate the expression and activity of MMP-2 and MMP-9, key enzymes involved in extracellular matrix degradation and tumor invasion." (PMID 38939095, 2024). "Studies using a 3D tumoroid model of metastatic CRC demonstrate that cisplatin and 5-FU, commonly used chemotherapeutics, stimulate MMP9 promoter activity within residual cancer cells, despite differing effects on overall tumor growth." (PMID 39664453, 2024). "The MMP family is associated with tumour progression, metastasis and angiogenesis of CRC, and the overexpression of MMP‐2 and MMP‐9 has been known as a sign of poor prognostic factors." (PMID 38506205, 2024). "IL33 drives MMP9 production via an NF-kB-dependent mechanism, leading to laminin degradation, which can be a critical step for tumor cell extravasation and invasion (path 2)." (PMID 39086395, 2024). "A pyrrole-imidazole (PI) polyamide specifically designed to bind to the activator protein-1 (AP-1) site on the MMP-9 promoter was developed and synthesized as a gene-silencing agent aimed at combating tumor metastases." (PMID 39858430, 2024). "MDSCs can also regulate VEGF bioavailability through inducing high levels of matrix metalloprotease 9 (MMP9) and pro-MMP9 to stimulate tumor growth and metastases in CRC." (PMID 39877377, 2024). "Plasmodium infection also inhibits tumor angiogenesis by blocking the IGF-1/MMP9 signaling pathway of TAMs in tumor tissue through the metabolite hemozoin of the parasite." (PMID 38807760, 2024). "Leptin can regulate other factors and pathways affecting bone resorption, such as matrix MMP2 and MMP9, which are involved in extracellular matrix remodeling, tumor progression, and bone absorption." (PMID 38571500, 2024). "MDSCs that infiltrate tumor tissues directly promote tumor growth and angiogenesis by secreting MMP9 and differentiating into ECs." (PMID 38404689, 2024). "Research indicates that MMP-2 and MMP-9 play significant roles in cancer cell proliferation and invasion, impacting tumor growth, aggressive progression, and patient survival in UTUC." (PMID 39063556, 2024). "To further validate the VM-promoting role of MMP9, we performed an in vitro treatment of MMP9 on EBV-positive tumour cells and subsequent VM formation assays." (PMID 39267775, 2024). "Taken together, based on both in vitro and in vivo analyses, our data reveal that MMP9 represents one of the key downstream effectors that contribute to SET-ZBTB11 complex-mediated regulation of tumor metastasis." (PMID 38355937, 2024). "Among the members of the MMP family, MMP-2 and MMP-9 are known to play a direct role in tumor metastasis." (PMID 39364049, 2024). "A low concentration of resveratrol profoundly inhibits the cell invasion of 4T1 tumour spheroids with a co-culture of embryonic stem cells via the reduction in the tumour’s MMP-9 expression." (PMID 38673959, 2024). "In LK0923 tumor cells, FMOD, MMP1 and MMP9 were significantly upregulated after coculture with both 0836CAF and 1001CAF compared to tumor-matched CAFs." (PMID 38822309, 2024).
tumor (continued). "Endothelial degradation primarily through matrix metalloproteinases MMP2, MMP7 and MMP9 is not only required for angiogenesis, but also promotes tumor migration and metastasis." (PMID 38935134, 2024). "Subsequently, experimental validation confirmed that MICA+ tumor cells upregulated MMP9 expression in macrophages through the PROS1-AXL axis." (PMID 38254761, 2024). "Immunofluorescence and immunohistochemistry analyses revealed significant colocalization between p-JNK, a representative MAPK pathway protein, and MMP9 within tumor tissues." (PMID 38907234, 2024). "Studying their effect on Hh signaling as well as on the expression of MMP-2 and MMP-9, which are involved in tumor progression, is interesting from the point of view of creating drugs with antitumor activity that can be used in various types of human cancer." (PMID 39274874, 2024). "Numerous studies have demonstrated abnormal expression of MMP2 and MMP9 in tissues following tumor occurrence." (PMID 38189823, 2024). "MMP2 and MMP9, members of the MMP family, are often involved in poor prognosis and linked to tumor invasion and metastasis in CRC y." (PMID 39520627, 2024). "This pattern is completely logical as inhibition of IL-10 allows for less immunosuppression, more angiogenesis, and more VEGF, IL-1β, TNF-α, IL-6, MMP-9, and NF-κB activation, which encourages tumor volume." (PMID 39451257, 2024). "This heightened MMP9 presence, driven by chemotherapy, not only poses a risk for the development of CIPN but also risks exacerbating cancer outcomes by facilitating tumor invasion and metastasis through its remodeling capabilities." (PMID 39664453, 2024). "MICA+ tumor cells stimulated the secretion of MMP9 from macrophages through the PROS1-AXL axis, thereby facilitating the proteolytic shedding of MICA into soluble MICA." (PMID 38254761, 2024). "In order to investigate the potential mechanism of BDS-hEA inhibiting HCC tumor growth, immunofluorescence staining was employed to analyze the expression changes of tumor proliferation (ki67), migration (MMP-9), and angiogenesis (CD31 and VEGF)." (PMID 39091624, 2024). "The results showed that glabridin downregulated MMP-9 by interfering with nuclear factor-κB (NF-κB) and AP-1 binding activity, ultimately inhibiting tumor cell invasion and metastasis." (PMID 39723390, 2024). "MMP-9 secreted by neutrophils, mast cells, and macrophages degrade the main components of the basement membrane to promote tumor invasion 18-20." (PMID 39247608, 2024). "The elevated expression and activity of MMP-2 and MMP-9 in tumor contexts instigate the breakdown of these basement membranes, a pivotal step in tumor invasion and the metastatic process." (PMID 38939095, 2024). "On the other hand, MMP-9, derived from inflammatory cells like neutrophils, mast cells, and macrophages, promotes tumor invasion and angiogenesis by facilitating the release of TGF- and VEGF." (PMID 39582871, 2024). "Matrix metalloproteinases (MMPs) have frequently been reported to facilitate tumor invasion and metastasis, with MMP-9 acting as one of the most important mediators of tumor migration and invasion." (PMID 39534596, 2024). "We also considered the potential cross-reactivity of the MMP-11 antibody with other MMPs, such as MMP2 (gelatinase A), MMP9 (gelatinase B), and MMP14 (membrane-type 1 MMP), which are commonly associated with tumor cells." (PMID 38438841, 2024). "Such behavior was consistent with that already observed in various inflammatory mechanisms, as well as in tumor invasion and migration, in which MMP-9 showed much more marked variations, even in the presence of mild stimuli." (PMID 39591310, 2024). "The decrease in MMP-9 activity along with MMP-1 or MMP-2 was observed in different tumor cell lines (HCC38, HCC1937, MDA-MB 231, A549) after treatment with blueberry extract or with the flavanone naringenin (100 μM)." (PMID 38540096, 2024).